NEUID (neuronal identity associated lncRNA)
Gene: Long non-coding RNA gene on chromosome 4 (576,404 to 618,108, forward strand). Ensembl gene ENSG00000283183.
Diseases named in the same sentence as NEUID in open-access papers:
NEUID is named in the same sentence as 1 disease in open-access papers, as found by Europe PMC text mining. Sharing a sentence is not in itself a finding about the gene and the disease.
NEUID shares sentences with these, for which no sentence is quoted: Alzheimer disease (1 paper).